WDR49 (WD repeat domain 49)
Description:
Associates with components of the nexin-dynein regulatory complex (N-DRC), a key regulator of ciliary/flagellar motility, and might act as an inner dynein arm (IDA) hub or linkage.
Synonyms: CFAP337; FLJ33620
Tractability: No criterion of Open Targets' tractability assessment is met for any kind of drug.
Gene: Protein-coding gene on chromosome 3 (167,477,789 to 167,653,983, reverse strand). Ensembl gene ENSG00000174776.
Subcellular location: Cell projection, cilium
Subcellular location (Human Protein Atlas): Nuclear bodies; Nucleoplasm; Basal body; Cytosol; Mitotic spindle; Primary cilium; Primary cilium tip; Primary cilium transition zone
Gene Ontology:
Molecular function: protein binding; calcium ion binding
Cellular component: cilium
Genetic constraint (gnomAD): Loss-of-function variants: 93 observed, 101.41 expected, observed/expected ratio (o/e) 0.92, 90% interval 0.77 to 1.09. The upper end of that interval is the gene's LOEUF score, 1.09, which puts it in group 4 of 6, group 1 being the genes least tolerant of losing a copy. Missense variants: 1,183 observed, 1,139.6 expected, observed/expected ratio (o/e) 1.04, 90% interval 0.99 to 1.09. Synonymous variants: 404 observed, 381.27 expected, observed/expected ratio (o/e) 1.06, 90% interval 0.98 to 1.15.
Homologues: Orthologues: pig WDR49 (80% identical), rabbit WDR49 (80% identical), dog WDR49 (78% identical), rat Wdr49 (76% identical), macaque WDR49 (70% identical), chimpanzee WDR49 (66% identical), tropical clawed frog wdr49 (55% identical), mouse Wdr49 (51% identical). Paralogues in human: EFCAB8 (24% identical), WDR64 (17% identical), FBXW7 (11% identical), TRAF7 (10% identical), BTRC (8% identical), FBXW11 (8% identical), FBXW9 (7% identical), WDR86 (6% identical), FBXW8 (6% identical), FBXW12 (5% identical), WDR54 (5% identical), PAAF1 (5% identical), and 2 more.
Diseases named in the same sentence as WDR49 in open-access papers:
WDR49 is named in the same sentence as 3 diseases in open-access papers, as found by Europe PMC text mining. Sharing a sentence is not in itself a finding about the gene and the disease. The quoted sentences say what the papers report.
cancer (1 paper, 2020). A tumor composed of atypical neoplastic, often pleomorphic cells that invade other tissues. "Among them, chr3:167293827 was located in the intergenic region and chr5:2276656 was located in the body region of WDR49, which were both hypomethylated in all 13 cancers." (PMID 32414326, 2020).
WDR49 also shares sentences with these, for which no sentence is quoted: breast carcinoma (1 paper); hepatocellular carcinoma (1).